MTOR (mechanistic target of rapamycin kinase)
Diseases named in the same sentence as MTOR in open-access papers (continued):
Sharing a sentence is not in itself a finding about the gene and the disease.
mitral valve diseases (2 papers, 2020 to 2025). "Conserved transcriptome signature in human mitral valve disease specimen with activation of mTOR signaling and increased integrin expression." (PMID 40392604, 2025). "We confirmed increased mTOR signaling and a conserved transcriptome signature in human specimens of sporadic mitral valve prolapse." (PMID 40392604, 2025). "Using neutralizing β1 integrin mAb in vivo, we demonstrated that β1 integrin is required for early mTOR activation and leukocyte recruitment in mitral valve disease as well as the later development of ECM changes characteristic of mitral valve degeneration." (PMID 40392604, 2025). "A key role for mTOR activity was established by complete rescue of the mitral valve disease phenotype by rapamycin treatment of mgR mice, in which the pathological process was dependent on both integrin and TGF-β signaling." (PMID 40392604, 2025). "Thus, mTOR activation from abnormal integrin-dependent cell–matrix interactions drives TGF-β overactivity and myxomatous mitral valve degeneration, and mTOR inhibition may prevent disease progression of mitral valve prolapse." (PMID 40392604, 2025). "The KEGG analyses revealed that the mTOR signalling pathway, circadian rhythm, ARVC, the metabolism pathway, mitral valve diseases and QT interval were important pathways." (PMID 32332808, 2020).
motor neuron disease (2 papers, 2017 to 2023). "It was recently demonstrated that the downregulation of Ataxin-2, a lipid-storage factor and mTOR-repressor upstream from PINK1, may postpone death in a mouse model of motor neuron disease from 20 to over 300 days." (PMID 28768533, 2017).
mucinous ovarian carcinoma (2 papers, 2016 to 2025). An invasive malignant neoplasm that arises from the ovary and is characterized by the presence of malignant epithelial cells that contain intracytoplasmic mucin and may resemble the epithelial cells of the endocervix or gastrointestinal tract. "The aim of this study was to clarify the synergistic effects of dual inhibition of the PI3K/mTOR and MAPK pathways in ovarian mucinous carcinoma (OMC) cells, using fluorescence resonance energy transfer (FRET) imaging." (PMID 27102436, 2016).
myasthenia gravis (2 papers, 2023 to 2024). Myasthenia gravis (MG) is a rare, clinically heterogeneous, autoimmune disorder of the neuromuscular junction characterized by fatigable weakness of voluntary muscles. "Myasthenia gravis patients' immune systems may be influenced by the PI3K/Akt/mTOR signalling pathway, according to these studies." (PMID 36818231, 2023).
mycosis fungoides (2 papers, 2021 to 2022). Classical mycosis fungoides is the most common type of mycosis fungoides (MF), a form of cutaneous T-cell lymphoma, and is characterized by slow progression from patches to more infiltrated plaques and eventually to tumors. "The PI3K/AKT/mTOR pathway may thus have had a marginal role, if a role at all, in the individual pathogenesis of mycosis fungoides in the included early-stage patients." (PMID 35326659, 2022).
myeloid malignancies (2 papers, 2016 to 2022). "In fact CK2 plays a critical triggering role in several survival pathways including the PI3K/Akt/mTOR, WNT, NF-κB, and JAK-STAT networks, both in lymphoid and myeloid tumors." (PMID 26593250, 2016).
neuropathic pain (2 papers, 2015 to 2020). Chronic pain caused by damage to nerve fibers. "We observed that the number of p-mTOR-positive neurons was significantly increased in the RVM on day 7 after SNI compared to the sham group, indicating that activation of mTOR in the RVM may contribute to SNI-induced neuropathic pain." (PMID 26770837, 2015).
Niemann-Pick disease (2 papers, 2022). A group of inherited, severe metabolic disorders in which sphingomyelin accumulates in lysosomes in cells. "The effects of NPC1 on lysosomal metabolism and mTOR signaling implicates autophagy in this model, and autophagy defects have been noted in Niemann–Pick disease models." (PMID 35884604, 2022).
Noonan syndrome (2 papers, 2021 to 2025). Noonan Syndrome (NS) is characterized by short stature, typical facial dysmorphism and congenital heart defects. "While sirolimus, a mammalian target of rapamycin inhibitor (mTOR), has been shown to suppress lymphangiogenesis, its efficacy in Noonan syndrome remains unclear." (PMID 41476857, 2025). "Given thatRIT1-related Noonan syndrome is caused by a gain of function in the RAS/RAF/mitogen-activated protein kinase signaling pathway, the mitogen-activated protein kinase inhibitor might be more effective than the mTOR inhibitor in such patients." (PMID 41476857, 2025).
ocular melanoma (2 papers, 2022 to 2024). A melanoma that arises from the structures of the eye or ocular adnexa. "However, in ocular melanoma cells, metformin did not sufficiently inhibit mTOR phosphorylation signal, which is also consistent with the study in neurons." (PMID 35075807, 2022).
oncocytoma (2 papers, 2011 to 2025). "Expression of both PI3K sub-units and mTOR was significantly higher in sarcomatoid tumors (P = 0.002, P = 0.04 and P = 0.02, respectively), and expression of p110α and mTOR was also significantly higher in oncocytomas." (PMID 21834980, 2011).
oral lichen planus (2 papers, 2013 to 2023). Oral lichen planus is a chronic inflammatory oral condition of unknown aetiology characterized by T-cell-mediated chronic immune response and abnormal epithelial keratinization cycle. "The purpose of this study was to evaluate the activation status of Akt, mTOR, and pS6 in oral lichen planus (OLP) in comparison with oral premalignant and malignant lesions and normal oral mucosa (NM)." (PMID 24228033, 2013).
oropharyngeal squamous cell carcinoma (2 papers, 2021). "The aim of the present study was to elucidate the role of the mTOR pathway in HPV-related oropharyngeal squamous cell carcinoma (OPSCC)." (PMID 33482765, 2021). "The molecular mechanism through which rapamycin inhibits the growth and proliferation of oral and oropharyngeal squamous cell carcinoma may lie in the inhibition of the PI3K/Akt/mTOR signalling pathway." (PMID 34900689, 2021).
osteogenesis imperfecta (2 papers, 2023 to 2024). Osteogenesis imperfecta (OI) comprises a heterogeneous group of genetic disorders characterized by increased bone fragility, low bone mass, and susceptibility to bone fractures with variable severity. "In summary, we have identified heterozygous variants in KIF5B as a novel cause of osteogenesis imperfecta with a dominant negative mechanism due to an intracellular trafficking defect and downregulation of mTOR signaling pathway." (PMID 37934770, 2023). "The study identifies KIF5B variants as a novel cause for osteogenesis imperfecta and suggests that mTOR signaling may be potentially targeted for future therapy in KIF5B-related disorder." (PMID 37934770, 2023). "Notably, reduced mTOR signaling has been previously implicated in mouse models of osteogenesis imperfecta." (PMID 37934770, 2023).
ovarian clear cell adenocarcinoma (2 papers, 2013 to 2014). A malignant glandular epithelial neoplasm characterized by the presence of clear and hobnail cells. "The PI3K/mTOR pathway is frequently activated in ovarian clear cell adenocarcinomas (OCCA) through various mutations that activate PI3K-AKT signaling." (PMID 24504419, 2014). "This study reports the involvement of stathmin in the mTOR/HIF-1α/VEGF pathway in ovarian clear cell adenocarcinoma (CCA) during hypoxia." (PMID 23819061, 2013).
Pca (2 papers, 2019 to 2022). "High levels of phosphorylated-4EBP1 and eIF-4E are significantly related to increased mortality in PCa patients, implying that downstream effectors of the mTOR pathway may be a potential prognostic indicator for PCa progression." (PMID 30754640, 2019). "BEZ235 was also reported to reduce tumor volume in a mouse model harboring PTEN loss, and the effects were enhanced when combined with AR antagonist enzalutamide, implying a potential prospect in synergy treatments cotargeting the AR, PI3K and mTOR signaling pathways in PCa." (PMID 30754640, 2019). "Studies in PCa cell lines indicated that the PI3K/Akt/mTOR pathway contributed to PCa radioresistance (RR) through mechanisms of intrinsic radioresistance, cancer cell proliferation and hypoxia, and in those PCa RR cell lines, the PI3K/Akt/mTOR pathway was the most active." (PMID 30754640, 2019). "In Pca, mTOR inhibitor-enhanced GAS5 expression in androgen-sensitive cell lines, and GAS5 silencing induced resistance to cytostatic effects of mTOR inhibitors in Pca cells." (PMID 35159022, 2022).
penile squamous cell carcinoma (2 papers, 2020 to 2024). "In addition, from clinical data, compared with normal tissues, the level of phosphorylated mTOR is higher in penile squamous cell carcinoma." (PMID 38583115, 2024). "An investigation has shown that high expression of p-mTOR is correlated with presence of LNM and advanced stage of penile squamous cell carcinoma." (PMID 32023262, 2020).
periventricular nodular heterotopia (2 papers, 2023 to 2024). Periventricular nodular heterotopia (PNH) is a brain malformation, due to abnormal neuronal migration, in which a subset of neurons fails to migrate into the developing cerebral cortex and remains as nodules that line the ventricular surface. "Mutations of NEDD4L lead to Akt–mTOR pathway deregulation and cause periventricular nodular heterotopia." (PMID 38526036, 2024).
pituitary carcinomas (2 papers, 2019 to 2025). A primary or metastatic malignant neoplasm affecting the pituitary gland. "Moreover, the association of TMZ and targeted therapies, as anti-VEGF factors (bevacizumab) or mTOR inhibitors (everolimus) were used in aggressive pituitary carcinomas, even if with limited data and efficacy, but to date no cases have been described in patients with CTP-BADX/NS." (PMID 41006788, 2025). "Thus, our findings indicate that everolimus, an mTOR inhibitor, which has been used for treating patients with rare pituitary carcinomas, may represent an effective therapy for the >10% of prolactinomas that are resistant to dopamine agonist therapy." (PMID 30445560, 2019).
pleomorphic xanthoastrocytoma (2 papers, 2021 to 2022). A WHO grade ll astrocytic tumor with a relatively favorable prognosis. "Examples are BRAF mutations in pleomorphic xanthoastrocytoma (PXA) and papillary craniopharnygeoma (PCP) as well as TSC mutations in subependymal giant cell astrocytoma (SEGAs) that can be targeted by BRAF or mTOR inhibitors (e.g. vemurafenib or everolimus)." (PMID 35864412, 2022).
pneumothorax (2 papers, 2016 to 2024). Abnormal presence of air in the pleural cavity. "Although management guidelines for LAM are mostly based upon studies of sporadic LAM, the similar disease manifestations of TSC-LAM suggest that their use in TSC is appropriate; particularly recommendations for mTOR inhibitor therapy and early surgical treatment for pneumothorax." (PMID 38532450, 2024).
Polycythemia Vera (2 papers, 2013 to 2014). "Co-treatment of mTOR inhibitor with JAK2 inhibitor resulted in synergistic activity against the proliferation of JAK2V617F mutated cell lines and significantly reduced erythropoietin-independent colony growth in patients with polycythemia vera." (PMID 23382981, 2013).
postmenopausal osteoporosis (2 papers, 2023). Metabolic disorder associated with fractures of the femoral neck, vertebrae, and distal forearm. "We hypothesized that KOK and P. lobata extracts could alleviate postmenopausal osteoporosis by stimulating autophagy-activating kinases, such as AMPK and ATG1/ULK1, and regulating mTOR levels." (PMID 37435569, 2023). "We confirmed that the KOK and P. lobata extracts effectively alleviated postmenopausal osteoporosis by regulating autophagy, which was related to the activation of AMPK and ULK1 by ginsenoside and honey in KOK, and regulation of mTOR expression by puerarin in P. lobata." (PMID 37435569, 2023).
primary aldosteronism (2 papers, 2022 to 2025). An endocrine disorder characterized by excessive production of aldosterone by the adrenal glands. "Overactive mTOR signaling has been demonstrated to contribute to primary aldosteronism; mTORC1 complex inhibition has been associated with decreased levels of plasma aldosterone and decreased blood pressure." (PMID 36551265, 2022).
pulmonary neoplasms (2 papers, 2016 to 2025). "Collective data indicated that pulmonary neoplasms of peripheral adenocarcinomatous lineage in BHD patients frequently exhibit LOH of FLCN with mTOR pathway signaling." (PMID 26974543, 2016).
retinal ischemia (2 papers, 2018 to 2025). A ischemic disease that involves the retina. "In a model of retinal ischemia/reperfusion injury, our group showed that inducing autophagy, either via the mTOR (mammalian target of rapamycin) inhibitor rapamycin or by starvation, significantly improved RGC survival." (PMID 41285704, 2025). "Based on the modulation of mTOR pathway following retinal ischemia/reperfusion injury, we used the mTOR inhibitor rapamycin to pharmacologically enhance autophagy in the retina." (PMID 30250019, 2018). "Retinal ischemia induced a transient dephosphorylation of mTOR (Ser2448), which corresponded with the kinase deactivation, as confirmed by the decreased phosphorylation of two mTOR downstream targets, ULK1 (Ser757) and 4EBP1 (Thr37/46)." (PMID 30250019, 2018).
Rotavirus infection (2 papers, 2018 to 2019). Infection with any of the rotaviruses. "In this study, we have dissected the effects of PI3K-Akt-mTOR signaling pathway on rotavirus infection using both conventional cell culture models and a 3D model of human primary intestinal organoids." (PMID 28475412, 2018). "Silencing of mTOR led to a significant reduction of rotavirus RNA, suggesting a supportive role of mTOR for rotavirus infection." (PMID 28475412, 2018). "We found that PI3K-Akt-mTOR pathway is crucial in sustaining rotavirus infection via its downstream effector 4E-BP1 and the induction of autophagy." (PMID 28475412, 2018). "In summary, we have dissected the effects of PI3K-Akt-mTOR signaling on rotavirus infection, and demonstrated that blocking this pathway can potently inhibit rotavirus replication." (PMID 28475412, 2018). "In this study, we comprehensively studied the role of PI3K-Akt-mTOR signaling in rotavirus infection and explored the avenues of therapeutic targeting." (PMID 28475412, 2018). "We found that PI3K-Akt-mTOR signaling is essential in sustaining rotavirus infection." (PMID 28475412, 2018). "Importantly, the mTOR inhibitor, rapamycin, induced autophagy machinery to inhibit rotavirus infection via 4E-BP1." (PMID 28475412, 2018). "mTOR is a central element of the PI3K-Akt-mTOR signaling pathway, we thus investigated its effect on rotavirus infection." (PMID 28475412, 2018). "Collectively, these data suggest that 4E-BP1 but not S6K is a downstream effector of the PI3K-Akt-mTOR signaling in sustaining rotavirus infection." (PMID 28475412, 2018). "However, this pathway is essential in sustaining rotavirus infection, and inhibition of PI3K-Akt-mTOR signaling resulted in potent anti-rotavirus activity." (PMID 28475412, 2018). "Although rotavirus infection did not directly affect the expression levels of the key components the PI3K-Akt-mTOR pathway, this pathway itself intrinsically sustained rotavirus infection." (PMID 28475412, 2018).
salivary gland tumors (2 papers, 2016 to 2020). "Previous studies have reported activation of mTOR following salivary gland injury, including duct ligation, irradiation and salivary gland tumors." (PMID 26958808, 2016).
Schaaf-Yang syndrome (2 papers, 2019 to 2021). "Recent studies have reported dysregulation of mTOR-dependent autophagy in other neurodevelopmental disorders including Schaaf-Yang syndrome (SHFYNG) and Koolen-de Vries syndrome (KdVS)." (PMID 34920755, 2021).
schistosomiasis (2 papers, 2019). An infectious disease caused by parasitic trematodes of the genus Schistosoma that colonize human blood vessels and release eggs that can cause granulomatous reactions leading to acute (swimmer's itch or acute schistosomiasis syndrome) or chronic disease. "In schistosomiasis, however, very little is known about the function of mTOR." (PMID 31681260, 2019). "mTOR expression is also enhanced in S. haematobium-associated bladder cancer, although this may be a general feature of malignancy rather than schistosomiasis." (PMID 31681260, 2019).
scrapie (2 papers, 2015 to 2017). A fatal disease of the nervous system in sheep and goats, characterized by pruritus, debility, and locomotor incoordination. "Herein, we studied the expression and distribution of REST in scrapie-infected hamsters, and REST expression and associated changes of the Akt-mTOR Wnt-β-catenin signaling pathways." (PMID 28515679, 2017). "More recently, we found that FBXW7 (F-box and WD repeat domain containing 7) is responsible for the induction of mTOR degradation and for the ability of endogenous autophagy to counteract prion replication in the scrapie infected cell line SMB-S1516." (PMID 26423766, 2015). "Coincidental with the decrease of mTOR in hamster brains infected with scrapie 263 K, the level of ULK1-Ser757, the downstream substrate of mTOR, increased transiently at the very early stage of infection but then quickly declined and was barely detectable at 70 dpi." (PMID 26423766, 2015).
skin aging (2 papers, 2016 to 2021). The gradual irreversible changes in structure of skin that occur as a result of the passage of time.. "mTOR pathway is one of well-known mediators of aging process, however, its role in skin aging has not been determined." (PMID 27486771, 2016). "However, there is no study to date that examined the function of mTOR signaling pathway in skin aging." (PMID 27486771, 2016).
Skin ulcer (2 papers, 2018 to 2022). A discontinuity of the skin exhibiting complete loss of the epidermis and often portions of the dermis and even subcutaneous fat. "Finally, BC of patients with skin ulcers reported a positive correlation with mTOR expression, while in patients without skin ulcers, a greater representation of PD-L1 was observed." (PMID 36556228, 2022).
SSADH deficiency (2 papers, 2014 to 2022). "The data presented here further emphasize the vital role of tightly regulated autophagy for cellular homeostasis and provide a proof of principle for using autophagy-inducing drugs or mTOR inhibitors for the treatment of SSADH deficiency and other disorders characterized by elevated levels of GABA." (PMID 24578415, 2014). "Furthermore, rapamycin, the mTOR inhibitor, abolished GABA-induced defects in yeast, and mammalian cells, as well as in murine models of heritable succinic semialdehyde dehydrogenase deficiency, which is an infrequent GABA metabolism defect." (PMID 35744783, 2022).
TAFRO syndrome (2 papers, 2022). "Several recent reports have indicated that IFN signaling was upregulated in some patients with TAFRO syndrome, and an inhibitor of mTOR, a molecule downstream of type I IFN signaling, was effective." (PMID 36211342, 2022). "Increased mechanistic target of rapamycin (mTOR) activation has been observed in the lymph nodes of patients with the iMCD-TAFRO syndrome, whereas the iMCD-TAFRO syndrome pathophysiology remains unclear." (PMID 36482523, 2022).